CTLA4 (cytotoxic T-lymphocyte associated protein 4)
Diseases named in the same sentence as CTLA4 in open-access papers (continued):
Sharing a sentence is not in itself a finding about the gene and the disease.
tumor (continued). "Additionally, one patient with MCC refractory to anti-PD-1 and anti-CTLA-4 experienced tumor regression with anti-PD-L1." (PMID 31287031, 2019). "However, ATOR-1015 was designed as a next generation CTLA-4 targeting antibody, with the aim of having a more favourable safety profile and better efficacy than current anti-CTLA-4 antibodies due to its tumor-directed activity." (PMID 30975201, 2019). "The blockade of CTLA-4, a negative regulator of T-cell responses, by ipilimumab may augment the endogenous anti-tumor cellular immune response, leading to tumor cell death." (PMID 31156623, 2019). "To address this issue, we considered whether pH sensitivity affects the bioavailability of anti-CTLA-4 antibodies and target density on tumor-infiltrating Tregs." (PMID 31267017, 2019). "It is speculated that sCTLA-4 might block the binding of membrane-bound CTLA-4 to its ligand and thus result in enhanced tumor immunity in synergy with ipilimumab." (PMID 31192215, 2019). "Taken together, these studies suggest that targeting immunosuppressive cells in conjunction with immunotherapies that target T cells, such as anti-CTLA4 and anti-PD-L1, could be effective treatment strategies for tumor metastases." (PMID 31488209, 2019). "Higher expressions of CTLA4 were significantly associated with the good survival outcomes in the TCGA BRCA (Her2+) and HNSC cancer patients after adjusting for the abundances of tumor infiltrating immune cells." (PMID 31358815, 2019). "ATOR-1015 is a next generation CTLA-4 targeting antibody with enhanced immune activation and tumor-directed activity, which may translate into improved clinical efficacy and reduced toxicity compared to anti-CTLA-4 monotherapy." (PMID 30975201, 2019). "CTLA-4 is also thought to kill Treg via ADCC at tumor site and shape vasculature in the TME." (PMID 31060225, 2019). "Therefore, the immune checkpoint inhibitors ipilimumab and nivolumab have a dual mode of action, directly targeting tumor cells expressing CTLA-4, PD-1, and PD-L1, and also by inhibiting the Treg response to tumors." (PMID 31192129, 2019). "The established anti-tumor activity of targeting the PD-1 signaling axis as a monotherapy in a variety of cancers coupled with a favorable toxicity profile when compared to CTLA-4 inhibition provided robust justification for selecting anti-PD-1 antibodies as the backbone of combinatorial strategies." (PMID 30621125, 2019). "Secondly, following ICI MAb-mediated targeting of CTLA4-/PD-1-expressing Tregs, effective recovery of anti-tumor immunity, and possibly development of IRAEs, appears to be dependent on a gut microbiota populated with commensal microorganisms conducive to immune system re-programming." (PMID 31616428, 2019). "CTLA-4 and PD-1 downregulate T cell response in lymphoid tissues and tumor microenvironments." (PMID 31998135, 2019). "T-regs modulate tumor-specific effector T-lymphocytes by producing immunosuppressive cytokines, such as IL-10 and TGF-β, consuming IL-2 or expressing the inhibitory molecule cytotoxic T-lymphocyte associated protein 4 (CTLA-4 or CD 152)." (PMID 30682772, 2019). "For example, immune checkpoint blockade therapies against CTLA-4, Program Death-1 (PD-1), and PD-L1 could restore glucose in the tumor microenvironment, resulting in an enhanced glycolytic activity in tumor infiltrating T lymphocytes (TILs) and IFN–production." (PMID 31416244, 2019). "Previous attempts to target CAFs by less specific αSMA knockout resulted in enhanced tumor growth and immunosuppression which could be reversed by combination with immune checkpoint blockade, anti-CTLA4." (PMID 30726287, 2019). "Further pre-clinical studies suggested that anti-CTLA-4 and anti-PD-1 therapies may have synergistic effects, increasing the numbers of TILs, reducing T-reg and retarding tumor growth." (PMID 30941125, 2019).
tumor (continued). "We hypothesized that dual CTLA-4/PD-1 blockade may increase the tumor immunity elicited by DNA vaccines and lead to a significant antitumor response in tumor-bearing mice compared to each treatment alone." (PMID 31150505, 2019). "This trial suggests that anti-PD-L1 plus anti-CTLA4 combination therapy could have a modest effect in patients previously pretreated for colorectal cancer with a pMMR tumor." (PMID 31447840, 2019). "In a study of lung adenocarcinoma, EMT markers were associated with enhanced tumor infiltration of CD4+Foxp3+ Tregs and upregulation of inhibitory immune checkpoint molecules such as programmed cell death (PD)-ligand (L) 1, PD-L2, TIM-3, B7-H3, and CTLA-4." (PMID 31096701, 2019). "The primary anti-tumor mechanism of CTLA-4 checkpoint blockade remains controversial." (PMID 30718660, 2019). "Ipilimumab was found to bind to the CTLA-4-expressing tumor cells." (PMID 30506221, 2019). "Alternatively, although Lag-3 is present on these tumor T cells, its actual capacity to repress their activation and function may be limited in comparison to that of CTLA-4 and PD-1." (PMID 31533840, 2019). "Nevertheless, one representative of this class of PD-1/PD-L1 inhibitors, MAX 10129, showed encouraging results in preclinical studies, e.g., anti-tumor efficacy in combination with an anti-CTLA4 antibody, and reportedly is undergoing further development towards clinical trials." (PMID 31151293, 2019). "Maximizing exposure of anti-CTLA-4 in TDLNs where cytotoxic T cells are activated against tumor Ags may improve anti-tumor responses and minimize dose dependent irAEs." (PMID 31754400, 2019). "Like tumor cells, cardiomyocytes might also employ the PD-1/PD-L1 and CTLA-4 pathways to prevent T cells from hyper-activation in physiological condition." (PMID 31849640, 2019). "Additionally, tumor-infiltrating CD4+ T cells upregulated programmed cell death protein-1 (PD-1), cytotoxic T-lymphocyte-associated protein-4 (CTLA-4), T cell immunoglobulin and mucin domain-3 (TIM-3) and lymphocyte-activation gene 3 (LAG-3)." (PMID 31921188, 2019). "Combination of anti‐CTLA4 and anti‐PD‐L1 antibodies further decreases the tumour growth." (PMID 30378264, 2019). "NSCLC patients received anti‐CTLA4 antibody may have beneficial effects from the circulating T cells activation, but anti‐CTLA4 antibody also promotes NSCLC cell proliferation via the tumour cell‐intrinsic CTLA4." (PMID 30378264, 2019). "Treatment using ipilimumab, a CTLA-4 targeting antibody, shows restoration of tumor immunity at the priming phase and extends survival in some patients, conversely anti-PD-1/PD-L1 antibodies seem to affect the malignancy by returning immune function in the tumor microenvironment." (PMID 31323785, 2019). "To investigate the potential checkpoint inhibitors in this PDA model, we examined the expression of programmed cell death protein 1 (PD-1), cytotoxic T-lymphocyte-associated protein 4 (CTLA-4), and lymphocyte-activation gene 3 (Lag-3) on T cells within the KPC tumor microenvironment." (PMID 30959852, 2019). "In addition to targeted tumor specific Treg depletion via CTLA-4 blockade, other pharmacologic targets have been demonstrated to yield improved degrees of tumor rejection and restoration of the anti-tumor immune response." (PMID 31681327, 2019). "CTLA-4 signaling is utilized by some tumor cells to evade T cell anti-tumor activity." (PMID 31847387, 2019). "In addition, hypoxia induces upregulation of CTLA-4 and PD-L1 on tumor cells via HIF-1α in several different mouse and human tumor cell lines." (PMID 30930892, 2019). "Combination of anti‐CTLA4 and anti‐PD‐1 antibodies increases PD‐L1 expression in the tumour tissue." (PMID 30378264, 2019). "Thus, inhibition of CTLA4 is thought to lower the threshold for anti-tumor T-cell activation/proliferation via increasing CD28 signaling." (PMID 31275310, 2019).
tumor (continued). "Pre-clinical evidence supports a rationale for combination therapy as, by blocking more than one of these pathways, including PD-1, LAG-3, and CTLA-4, may reduce tumor growth." (PMID 30941125, 2019). "Similarly, in mice that have received orthotopic injection of 4T1 mammary tumor cells, the anti-PD1/anti-CTLA4 treatment in combination with CB-1158 significantly reduces growth of the primary tumor and decreases the number of lung metastases." (PMID 29670880, 2018). "Here, endogenously generated anti-tumor immunity could be maintained during dexamethasone treatment if CTLA-4 blockade was provided." (PMID 29891009, 2018). "CTLA-4 may be expressed in tumor lesions on infiltrating Tregs or exhausted conventional T cells as well as tumor cells themselves." (PMID 29644214, 2018). "This could also explain why combined anti-CTLA-4 + anti-PD-1 checkpoint blockade is particularly effective since anti-CTLA-4 would deplete Tregs whilst anti-PD-1 would directly dampen tumor glycolysis by inhibiting the mTOR pathway." (PMID 30191140, 2018). "VSV in combination with a CTLA-4 antibody was able to amplify a reproducible and statistically significant antitumor T cell immunologic response in murine mammary tumors, eliminating established macroscopic tumor implants." (PMID 29857493, 2018). "Under tumor development, TILs face a hostile environment that induces exhaustion to impair their antitumor activity, which is characterized by the up-regulation of immune checkpoints, such as CTLA-4, PD-1, and Tim-3." (PMID 30619178, 2018). "This failure in the setting of higher tumour burden might be attributed to the treatment-induced adaptive immune resistance, as evidenced by the elevated PD-1, PD-L1, and CTLA-4 expression in tumours." (PMID 30410056, 2018). "Furthermore, PD-1 expressed more broadly than CTLA4 in the T-cells in the tumor microenvironment has been found to reduce T-cell activity in the peripheral tissues." (PMID 29692957, 2018). "In parallel, by qRT-PCR, we observed a higher CTLA-4 expression in more advanced Masaoka-Koga grade IIB, III and IV compared to I and IIA, suggesting that CTLA-4 overexpression may be related to tumor aggressiveness." (PMID 29682176, 2018). "The high expression of CTLA-4 in tumor-infiltrating Treg cells and the presence of innate effector cells expressing high levels of CD16 and CD32a activatory FcγRs both in mouse and humans likely explain the preferential local depletion in the tumor by both antibody isotypes." (PMID 29576375, 2018). "Anti-CTLA-4 antibodies enhance tumor-specific immunity through a variety of mechanisms including: blockade of CD80 or CD86 binding to CTLA-4, repressing regulatory T cell function and selective elimination of intratumoral regulatory T cells via an Fcγ receptor-dependent mechanism." (PMID 29617360, 2018). "As a CI therapy, therefore, antibody blockade of CTLA-4 functions at a fundamental level to restore effective DC priming of naïve T cells, inducing full activation and expansion of nascent effector T cell populations against tumor neoantigens." (PMID 30319637, 2018). "Different cellular and murine models have been used to demonstrate that drugs inducing CTLA-4 blockade, used alone or in combination with other therapeutic interventions, improves endogenous responses to several tumor types, leading to tumor cell death when utilized." (PMID 29682176, 2018). "Interestingly, a recent study revealed that tumor cell-intrinsic CTLA-4 expression had an impact on the expression of PD-L1, as well as on tumor cell proliferation." (PMID 30577587, 2018). "The capacity of the tumor cells to evade destruction by CTLs could be bypassed by treatment with anti-PD-1 and anti-CTLA-4 antibodies, reinforcing the adaptive arm of the immune system." (PMID 30248992, 2018).
tumor (continued). "Importantly, pancreatic cancer mouse models have demonstrated that targeting CTLA4 in Tregs increases the infiltration of CD4+ T cells recruited to the tumor, suggesting that targeting Tregs is important for PDAC immunotherapy." (PMID 30428588, 2018). "As mentioned, anti-CTLA-4 in tumor models has shown to increase T-cell movement in the tumor." (PMID 30542345, 2018). "Indeed, depletion of T regulatory cells has been shown to improve anti-tumor immune response, while presence of myeloid-derived suppressor cells correlated with decreased anti-CTLA-4 response." (PMID 29968076, 2018). "Taken together, under CTLA-4 blockade, immune surveillance may be enhanced to sites where T-cells have restricted for tumor entry such as in peri-tumor sites where T-cells can be paralyzed." (PMID 30542345, 2018). "However, constitutive expression of CTLA-4 was found only on tumor Tregs, providing a rationale for selective depletion of this cell type from tumors by ADCC or antibody-dependent cellular phagocytosis." (PMID 29032503, 2018). "Administration of Ctla-4 blocking antibody reversed changes in immune infiltrate as well as tumor vasculature and histology suggesting that observed changes may be rooted in altered tumor immune response following myofibroblast depletion." (PMID 30108679, 2018). "Finally, antigen-specific T cell immunity against shared tumor-associated antigens (gp-100, MART-1, NY-ESO-1) are boosted with CTLA4 blockade and tend to be durable." (PMID 29973204, 2018). "Besides CTLA-4, engagement of PD-1 by PD-L1 expressed on tumor cells or T cells also inhibits antitumor T cells." (PMID 29467463, 2018). "However, the combination of anti-Ly6G and anti-CTLA-4 antibodies induced a complete tumor rejection." (PMID 29942309, 2018). "Consequently, inhibition of CTLA-4 by monoclonal antibodies such as ipilimumab and tremelimumab promotes anti-tumor immunity." (PMID 30170622, 2018). "Several cancer cell lines and tumor sections have been identified to express CTLA-4 with some evidence that some may also be able to produce sCTLA-4 to suppress effector T cell responses." (PMID 30319637, 2018). "The promising anti-tumor activity of mAbs targeting the immune-checkpoint proteins, such as cytotoxic T-lymphocyte antigen-4 (CTLA-4), programmed cell death protein 1 (PD-1), and the PD-1 ligand (PD-L1), led to regulatory approvals of these agents for the treatment of a variety of malignancies." (PMID 29910800, 2018). "The clinical implication of CTLA-4 expression in tumors or immune cells in the tumor microenvironment is still controversial, and the potential for CTLA-4 as prognostic and therapeutic marker has been complicated by differences in study population, methods and histological tumor types." (PMID 29682176, 2018). "Additionally, while comparing the methylation status of tumor tissues between the eight patients, DNA demethylation percentage of CTLA-4 in TT looks more consistent than the other five genes." (PMID 29983831, 2018). "Moreover, radiotherapy and CTLA-4 blockade were effective in inducing a systemic anti-tumor T cell response in chemo-refractory metastatic NSCLC that failed to respond to anti-CTLA-4 antibodies alone or in combination with chemotherapy." (PMID 30577587, 2018). "Local accumulation of extracellular adenosine suppresses DCs and Teff cells while promoting proliferation of Tregs, increases the expression of CTLA-4 and adenosine receptor 2A (A2AR) on Tregs, and enhanced the polarization of tumor-associated macrophages (TAMs) into an M2 suppressive phenotype." (PMID 30766539, 2018). "When combining the NP-R@M-M immunity and anti-CTLA-4 antibody, tumor proliferation could be effectively inhibited, and about half of the mice could survive at least 45 days free of tumor." (PMID 30406152, 2018).
tumor (continued). "Oncoviral tumor-localized delivery of this mAb may improve the therapeutic window for CTLA-4 targeted checkpoint intervention, allowing better tolerated and more effective combination therapy with approved antibodies targeting the PD-1/PDL1 axis." (PMID 30400822, 2018). "Therefore, anti-CTLA-4 antibodies can re-activate suppressed T lymphocytes, stimulating their proliferation and triggering humoral and cytotoxic anti-tumor response." (PMID 30545122, 2018). "However, radiation therapy combined with anti-CTLA-4 monoclonal antibody treatment has made great progress in anti-tumor practice." (PMID 29958545, 2018). "In fact, tumor-infiltrating T cells often have a dysfunctional (exhausted) phenotype that is characterized by impaired effector functions and increased expression of CTLA-4 and other inhibitory molecules." (PMID 30127783, 2018). "Considering the physiological role of CTLA-4, the blockade of this molecule in the context of a tumor immunotherapy would be important to directly enhance the functional properties of effector T cells as well as for inhibiting Treg cell-mediated immunosuppression of effector T cells." (PMID 29494517, 2018). "These blocking antibodies inhibit the interaction of CTLA-4 or PD-1 receptors on T-cells with their ligands on tumor cells or antigen-presenting cells and can reinvigorate tumor-reactive T-cells that have become dysfunctional or exhausted in the immunosuppressive tumor microenvironment." (PMID 29348598, 2018). "Preferential depletion of tumor-infiltrating Treg cells by antibodies targeting CTLA-4, GITR, and OX40 depends upon both a higher density of the target molecule on intra-tumoral Treg cells compared with Teff cells and the presence of an appropriate population of cells to mediate ADCC." (PMID 29576375, 2018). "Tumor control by 8 Gy x4 plus anti-CTLA4 was also eliminated when pre-existing immunity was blocked (p < 0.05), indicating that this treatment regimen is also dependent on pre-existing immunity for tumor control." (PMID 29725089, 2018). "It is also possible that CTLA-4 blockade may inactivate tumor-infiltrating T-reg, although our prior work in this model did not implicate T-reg infiltration following immune cell depletion studies." (PMID 29377881, 2018). "Checkpoint inhibition (i.e., antibodies directed against pathways involved in adaptive peripheral immune suppression, such as CTLA-4, PD-1 and PD-L1) is an especially promising anti-tumour strategy that appears to be clinically relevant across a number of tumour types." (PMID 29393888, 2018). "We, therefore, tested whether the combination of vvDD/vvDD-IL-2-RG and anti-PD-1/PD-L1 or anti-CTLA-4 antibody could improve the therapeutic effects using the late-stage tumour model." (PMID 30410056, 2018). "In addition, Th17 cells, which are implicated in many autoimmune and chronic inflammatory disorders and in tumor eradication processes, are also affected by CTLA-4 blocking." (PMID 29520282, 2018). "Survival curves were calculated according to univariate analysis and the Kaplan–Meier method by evaluating the age (≤ 60 vs > 60 years), sex, MG, invasion phenotype, invasion localization (capsular vs extra-capsular), tumor dimensions ≤ 5 cm or > 5 cm, radicality and CTLA-4 mRNA expression." (PMID 29682176, 2018). "In addition, the use of broad-spectrum antibiotics to eliminate gut microbiota altered the anti-tumor effect of anti-CTLA-4 therapy." (PMID 30073150, 2018). "They found that infusion of higher numbers of TIL with CD8 predominance and expression of BTLA (B And T Lymphocyte Associated) by the tumor cells correlated with improved response in anti-CTLA4 naïve patients, but not in anti-CTLA4 refractory patients." (PMID 30577797, 2018). "Moreover, this therapy sensitized the tumor for anti-PD-1 and anti-CTLA-4 antibodies, since the combination therapy led to an increased tumor regression and prolonged mouse survival as compared to the therapy with ICI alone." (PMID 29942309, 2018).